FASN (fatty acid synthase)
Diseases named in the same sentence as FASN in open-access papers (continued):
Sharing a sentence is not in itself a finding about the gene and the disease.
viral infection (continued). "This represents a novel mechanism of virus infection regulation, which has not been reported in other viruses, although the FASN protein is involved in the regulation of multiple viruses through distinct mechanisms." (PMID 41196069, 2025). "Since the virus productive infection leads to re-localization of the Golgi apparatus, it is no wonder that the Golgi harboring FASN will show a distinct distribution profile in response to viral infection." (PMID 41196069, 2025). "The dramatic depletion of FASN protein in Neuro-2A cells induced by viral infection was not due to virus-induced cell death, as determined by the CCK-8 assay." (PMID 41196069, 2025). "Our results indicated that FASN protein was readily detected in the Golgi fractions, regardless of viral infection." (PMID 41196069, 2025). "The decreased steady-state protein levels of FASN do not corroborate the increased mRNA levels in response to viral infection." (PMID 41196069, 2025). "The colocalization between FASN and the cloned viral proteins (NS3 and NS5) in transfected cells might not reflect the reorganization of the host and viral proteins upon virus infection, where ancillary proteins may play a significant role." (PMID 40131913, 2025). "Another limitation is the lack of knowledge on the mechanistic role of FASN during viral infection, and several variables warrant further investigation." (PMID 40558086, 2025). "FASN-KO HEK293T-hACE2 cells are also resistant to virus infection, and eleven out of 22 FAS inhibitors blocked SARS-CoV-2-mNG infection, the most effective ones being TVB-3664, orlistat, TVB-2640, TVB-3166, GSK-214069, FASN-IN-4, and FT113." (PMID 38106410, 2023). "We have therefore hypothesized that measurement of circulating FASN may provide a direct link between HIV and/or HCV viral infections and lipid metabolic disorders commonly observed in HIV/HCV-infected patients." (PMID 20707918, 2010). "It is plausible, therefore, that increased levels of serum FASN are not a mere epiphenomenon related to cell destruction and leakage but rather to a pathophysiologic response occurring during the viral infection." (PMID 20707918, 2010). "The present study aimed to investigate whether serum FASN concentration may provide a direct link between HIV and/or HCV viral infections and lipid metabolic disorders commonly observed in HIV/HCV-infected patients." (PMID 20707918, 2010). "We found that a subset of FASN protein co-localized well with the Golgi marker protein GP73, regardless of viral infection, indicating its accumulation in the Golgi apparatus (zoom-in areas)." (PMID 41196069, 2025).
Hyperglycemia (21 papers, 2010 to 2025). An increased concentration of glucose in the blood. "In this regard, visceral FASN mRNA levels have been previously found inversely associated with BMI and hyperglycemia." (PMID 36769659, 2023). "Hepatic FASN deficiency in ob/ob mice improves glucose tolerance and confers relative fasting hypoglycemia but exacerbates hyperglycemia in the fed state." (PMID 37681411, 2023). "The exacerbation of fed hyperglycemia by hepatic FASN ablation in leptin-deficient mice appeared attributable to impairment of hepatic glucose uptake triggered by hepatic glycogen accumulation and citrate-mediated inhibition of glycolysis." (PMID 37681411, 2023). "In contrast, in ob/ob mice, loss of hepatic FASN resulted in marked exacerbation of fed hyperglycemia despite a greater suppression of gluconeogenesis compared with that apparent in Mc4r-KO mice." (PMID 37681411, 2023). "In Mc4r-KO mice, hepatic FASN deficiency ameliorated hyperglycemia in the fed state." (PMID 37681411, 2023). "The fact that hepatic FASN deficiency exacerbates fed hyperglycemia only on the ob/ob genetic background may be explained by the increased hepatic citrate levels apparent in ob/ob HKO mice but not in Mc4r-KO HKO mice." (PMID 37681411, 2023). "We found that silencing FASN reversed the effects of hyperglycaemia on the levels of EMT markers leading to increased expression of E-cadherin and decreased vimentin and fibronectin." (PMID 29331414, 2018). "Our mechanistic studies identified caveolin-1 as the major driver of the pro-invasive phenotype triggered by targeting FASN or the ERα during hyperglycaemia-induced, matrix-specific EMT." (PMID 29331414, 2018). "To understand the mechanism of hyperglycaemia-induced, matrix-specific EMT we focused on our previously defined signalling pathway implicating FASN and the downstream ERα in the regulation of hyperglycaemia-induced chemoresistance." (PMID 29331414, 2018). "Our earlier work in the MCF-7 and T47D cells identified FASN as a key mediator of hyperglycaemia-induced chemoresistance." (PMID 29331414, 2018). "We have previously shown that hyperglycaemia-induced chemo-resistance is dependent on FASN and ERα phosphorylation and translocation to the nucleus." (PMID 29088813, 2017). "The hyperglycaemia-induced chemo-resistance and increases in FASN and IGFBP-2 were negated in a hypoxic environment, with levels of cell death unaffected by glucose concentrations." (PMID 29088813, 2017). "Researchers also found that FTO can facilitate mRNA expression of FOXO1, fatty acid synthase (FASN), G6Pase catalytic subunit (G6PC), and diacylglycerol acyltransferase 2 (DGAT2), whose increased expression is closely associated with hyperglycaemia and dyslipidaemia in T2DM patients." (PMID 40410881, 2025). "We also attempted to block the hyperglycaemia-induced EMT phenotype by targeting the lipogenic enzyme fatty acid synthase (FASN) and the downstream ERα which, as previously shown by us, cooperate together to mediate hyperglycaemia-induced chemoresistance in these cells." (PMID 29331414, 2018). "Furthermore, we recently showed that ERα functions as a downstream effector of FASN in the context of hyperglycaemia-induced chemoresistance." (PMID 29331414, 2018). "We speculated that FASN might be a likely candidate in mediating the hyperglycaemia-induced, matrix-specific EMT observed in our cell model." (PMID 29331414, 2018). "We have previously shown that FASN contributes to hyperglycaemia-induced chemo-resistance." (PMID 29088813, 2017). "The results of the present study also demonstrate that adipose FASN gene expression is higher in normoglycemic individuals compared to those with hyperglycaemia, together with lower values of BMI, TG and obviously glucose, HOMA-IR, and HbA1c levels in normoglycemics." (PMID 20148112, 2010).
Hyperglycemia (continued). "Moreover, hyperglycemia and hyperinsulinemia in a fetus lead to an increase of glucose uptake through glucose transporter 4, and it turns into fatty acid through increased expression of fatty acid synthase and acetyl coenzyme A carboxylase." (PMID 39832134, 2025). "We found that ATP citrate lyase (ACLY), acetyl-Co-A carboxylase (ACACA) which converts acetyl-CoA into malonyl-CoA, fatty acid synthase (FASN) and acetyl-CoA desaturase (SCD) were increased in normoglycemia in MIC26 KOs but mostly unchanged in hyperglycemia." (PMID 39393820, 2024). "Since FASN and IGFBP-2 confer resistance to chemotherapy in high glucose, reducing FASN and IGFBP-2 abundance negated the effect of hyperglycaemia under hypoxia." (PMID 29088813, 2017). "We did not observe any significant change in the protein levels of FASN during hyperglycaemia-induced, matrix-specific EMT with cells grown on fibronectin." (PMID 29331414, 2018). "Furthermore, hyperglycemic cultures had elevated FASN and SREBF1 gene expression, whereas the expression of MLXIPL was unchanged by hyperglycemia as compared to normoglycemic cultures." (PMID 27312339, 2016). "Given that targeting FASN during hyperglycaemia-induced, matrix-specific EMT was clearly not a good therapeutic approach, as it increased the invasive potential of the cells, we next determined whether targeting downstream ERα signalling would have a similar effect." (PMID 29331414, 2018).
lipid metabolism disorders (21 papers, 2010 to 2025). "Specifically, CX alleviates hepatic lipid metabolism disorders by enhancing antioxidant capacity, repairing hepatic tissue damage, and upregulating the expression of lipid synthesis-related genes (FASN, ACC, ME, SREBP-1c, and LXRα)." (PMID 40538726, 2025). "Progression of lipid metabolism disorder-related HCC is associated with the downregulation of AP-2α and the upregulation of SREBP1c/ACC/FASN in mice and patients." (PMID 40180937, 2025). "It has been reported that SREBP-1, SCD-1, and FASN are involved in the regulation of lipid synthesis, and their abnormal expression can lead to lipid metabolism disorders." (PMID 37297416, 2023). "High levels of pantetheine 4′-phosphate may lead to lipid metabolic disorder characterized by an increase in the synthesis of fatty acid synthase, which may promote NAFLD development or NASH progression." (PMID 38421203, 2024). "Studies have shown that Lactobacillus species can affect cholesterol oxidase and fatty acid synthase, as well as redistribute TG and cholesterol in the liver and blood, thereby improving lipid metabolism disorders and intestinal hepatic circulation of bile acid." (PMID 35450051, 2022). "AMPK activation inhibits downstream targets fatty acid synthase (FASN) and sterol element regulatory protein (SREBP-1c), regulating hepatic lipid metabolism disorders." (PMID 40873448, 2025). "The results of this study support the concept that TRIM21 improves hepatic glucose and lipid metabolic disorders through its binding to PEPCK and FASN." (PMID 37249651, 2023). "To investigate whether PEPCK1 and FASN were involved in the suppressive effect of TRIM21 on hepatic glucose and lipid metabolic disorders, we injected Ad-PEPCK1 and/or Ad-FASN into HFD-fed mice with TRIM21 overexpression." (PMID 37249651, 2023). "Our results showed that Dp3-Sam treatment suppressed the ACC, FASN, SREBP-1 C, and HMGCR expression in the liver tissue of HFD rats, indicating that lipid metabolism disorders could be improved by Dp3-Sam intervention." (PMID 34281481, 2021).
lymphoma (20 papers, 2012 to 2025). A malignant (clonal) proliferation of B- lymphocytes or T- lymphocytes which involves the lymph nodes, bone marrow and/or extranodal sites. "Our investigations indicate that upregulation of fatty acid synthase (FASN) and de novo lipogenesis, commonly observed in many cancers, are associated with nucleotide metabolic dysfunction in lymphoma." (PMID 34765544, 2021). "With respect to molecular docking studies, we used Bcl-2, DHFR, HMG-CoA reductase, and FASN as targets and the three terpenoids with the best cytotoxic and anti-lymphoma activity obtained in in vitro and in vivo studies as ligands." (PMID 40565145, 2025). "FASN is also the most highly overexpressed protein in almost all malignancies, including in lymphoma." (PMID 39518046, 2024). "The high cell proliferative ability of lymphoma cells correlates with upregulated expression of FASN." (PMID 37256177, 2023). "With FASN upregulation and unapparent effect on oxidative PPP genes, FASN is likely to function as an enzymatic driver of oxidative PPP in lymphoma tumors." (PMID 34765544, 2021). "In summary, FASN upregulation, generally ascribed with lipogenic function in malignancy, appears to be necessary for promoting nucleotides in lymphoma." (PMID 34765544, 2021). "Treatment of lymphomas with Orlistat, which is a lipase and fatty acid synthase (FASN) inhibitor, stopped tumor growth in vivo." (PMID 33291682, 2020). "Fatty acid synthase (FASN) plays a critical role in the pathogenesis of lymphoma." (PMID 36982568, 2023). "Moreover, inhibition of fatty acid synthase (FAS) resulted in significantly more necrotic CD37KO lymphoma cells." (PMID 36100608, 2022). "For examples, upregulation of fatty acid synthase (FASN) and de novo lipogenesis are found to associate with the development to a more aggressive phenotype of NHL while inhibition of FASN can induced apoptosis in lymphoma cells and improving antitumor efficacy of chemotherapy." (PMID 35279210, 2022). "Our study is the first demonstration that LC exhibits anti-tumor activity in lymphoma by targeting palmitoylation and fatty acid synthesis, suggesting that ZDHHC21/FASN axis can potentially be a promising therapeutic target for patients with DLBCL." (PMID 38195819, 2024). "Thus, FASN might be a potential therapeutic target for lymphoma therapy." (PMID 36982568, 2023). "We altogether conclude that FASN PGDH enzymes exhibit metabolic cooperativity and facilitate the flow of glucose carbons through PPP metabolism into the nucleotide biosynthesis in lymphoma." (PMID 34765544, 2021). "The results from these experiments led us to conclude that NADP–NADPH turnover and the reciprocal stimulation of FASN and PGDH catalysis are involved in promoting oxPPP and nucleotide biosynthesis in lymphoma." (PMID 34765544, 2021). "The fatty acid synthase FASN was overexpressed and thereby the lymphoma was more sensitive to the FASN inhibitor C75 than primary B cells." (PMID 31817676, 2019). "However, we found no change in FASN protein expression after 24 h hypoxia, but we observed a hypoxia-induced FAs profile consistent with previously reported data showing lymphoma cells scavenging fatty acids in hypoxia." (PMID 25605240, 2015).
nonalcoholic fatty liver disease (19 papers, 2017 to 2025). "The beneficial effects of hepatic FASN deficiency on nonalcoholic fatty liver disease and glucose metabolism are associated with the inhibition of de novo lipogenesis and the attenuation of gluconeogenesis and fatty acid oxidation, respectively." (PMID 40339699, 2025). "In addition, FASN has been implicated as a KD in numerous studies for nonalcoholic fatty liver disease, again highlighting the importance of this gene in common metabolic disorders." (PMID 33561811, 2021). "FASN is a key enzyme in hepatic de novo lipogenesis and is often upregulated in diseases such as nonalcoholic fatty liver disease and type 2 diabetes." (PMID 40339699, 2025). "SREBP1 is a critical regulator of lipid metabolism, in which it promotes expressions of lipogenic genes such as FASN and ACC, and it plays an important role in nonalcoholic fatty liver disease." (PMID 28449683, 2017). "In non‐alcoholic fatty liver disease, the mitochondrial pyruvate carrier (MPC1) suppression alters hepatocyte lactate levels and modifies lactylation patterns of multiple proteins, with fatty acid synthase (FASN) being most prominently affected." (PMID 41190507, 2025). "Fatty acid synthase (FAS) is a multifunctional enzyme involved in the production of fatty acids for lipid biosynthesis and is overexpressed in multiple diseases like cancer, viral, nonalcoholic fatty liver disease, and metabolic disorders." (PMID 35242140, 2022).
type 2 diabetes (19 papers, 2010 to 2025). "Deregulation of fatty acid synthase activity, chronic inflammation and oxidative stress may also contribute possible pathogenic mechanism for increased risk of breast and endometrial cancers in type 2 diabetes." (PMID 23826297, 2013). "Higher insulin levels in type 2 diabetes (T2D) can result in lipolysis of adipose tissue activating lipid synthesizing enzymes such as fatty acid synthase and stearoyl-CoA desaturase-1, resulting in lipid accumulation in liver." (PMID 40630828, 2024). "Forexample, fatty acid synthase (FAS) activity is associated withmyocardial infarction, hypertension, type II diabetes, and otherdiseases." (PMID 38223851, 2023). "We have also found higher concentrations of circulating FASN in patients with type 2 diabetes." (PMID 20707918, 2010). "Considering the bidirectional relationship between NASH and type II diabetes, we envisioned that PTM might be effective against the development NAFLD by targeting FASN similarly." (PMID 35052685, 2021).
prostate tumor (17 papers, 2007 to 2025). "FASN protein expression has previously been shown to be increased in prostate tumors harboring underlying ERG gene rearrangements compared with those without ERG rearrangements." (PMID 38112617, 2024). "FASN expression is also significantly increased in prostate tumors from carriers of the germline HOXB13 G84E mutation compared with matched controls, consistent with a report that HOXB13 may contribute to epigenetic regulation of FASN in vitro." (PMID 38112617, 2024). "Primary prostate tumors with ERG gene rearrangement have increased FASN expression and we find evidence of FASN hypomethylation in this context." (PMID 38112617, 2024). "We demonstrate that FASN protein is upregulated and the FASN gene is concomitantly globally hypomethylated in primary prostate tumors compared with normal tissue across multiple independent datasets." (PMID 38112617, 2024). "Consistent with our findings and the possibility of epigenetic regulation, FASN was also recently identified in a larger screen of hypomethylated and transcriptionally upregulated genes in TCGA primary prostate tumor cohort." (PMID 38112617, 2024). "In vivo, inhibiting the transcription factors sterol regulatory element binding proteins (SREBPs), that drive FASN expression, by fatostatin blocks both prostate tumor growth and distant metastasis." (PMID 36934087, 2023). "Further analysis of prostate tumour lysates revealed that up-regulation of PPARG correlated with increased levels of its downstream metabolic effectors such as Fatty acid synthase (FASN), acetyl-CoA carboxylase (ACC) and ATP citrate lyase (ACLY)." (PMID 33654198, 2021). "In this study, FBRA upregulated the expression of AMPK and downregulated the expression of FASN and cyclin D1 in prostate tumors." (PMID 27409632, 2016). "We provided evidence that P300 transcriptionally upregulates FASN expression and promotes lipid accumulation in human PCa cells in culture and Pten knockout prostate tumors in mice." (PMID 26934656, 2016). "MT63–78, a novel selective activator of AMPK, decreases prostate tumor growth and inhibits FASN and SREBP1c expression, and the anti-growth effects of this activator are mediated by the inhibition of lipogenesis." (PMID 26002551, 2015). "We demonstrate that the FASN gene body is hypomethylated and overexpressed in primary prostate tumors compared with benign tissue, and FASN gene methylation is significantly inversely correlated with FASN protein or gene expression in both primary and metastatic prostate cancer." (PMID 38112617, 2024). "The FASN overexpression is consistently found in prostate tumors." (PMID 35053570, 2022). "FASN staining was higher in breast and prostate tumours compared with the adjacent normal mucosa." (PMID 34887515, 2021). "Notably, at least one prior study has also suggested that FASN gene amplification may also be more common among prostate tumors from self-identified BL compared with WH patients." (PMID 38112617, 2024). "This treatment led to a decrease in prostate tumor formation, along with a 60–70% decrease in the enzymes acetyl-CoA carboxylase (ACC) and fatty acid synthase (FASN)." (PMID 40231924, 2025). "Key enzymes and transcription factors, such as FASN, ACLY, SREBPs, and FABPs, which are mainly regulated by androgen receptor signaling, orchestrate a lipogenic phenotype that supports prostate tumor growth and survival." (PMID 41009695, 2025). "Other important factors of TME which promote MDR are the overexpression of fatty acid synthase (FASN) and fatty acid-binding proteins (FBAP4, FBAP5, FBAP9) in breast/prostate tumor cells." (PMID 31936346, 2020). "We found that upregulation of FASN correlated with induction of many HIF target genes, notably in a malignant subtype of prostate tumours." (PMID 28775317, 2017).